FOXO1 (forkhead box O1)
Diseases named in the same sentence as FOXO1 in open-access papers (continued):
Sharing a sentence is not in itself a finding about the gene and the disease.
endothelial dysfunction (18 papers, 2016 to 2025). In vascular diseases, endothelial dysfunction is a systemic pathological state of the endothelium (the inner lining of blood vessels) and can be broadly defined as an imbalance between vasodilating and vasoconstricting substances produced by (or acting on) the endothelium. "Altogether, TPP-HT simultaneously suppresses the activation of p38 MAPK induced by PA and activates FoxO1 and Nrf2, which together combats oxidative stress and inflammation in hyperlipidemia-associated endothelial dysfunction." (PMID 36671037, 2023). "The plausible mechanisms by which FOXO1 causes some features of endothelial dysfunction include the controlling of the expression of both isoforms of nitric oxide synthase enzyme i.e. inducible and endothelial isoforms." (PMID 26956801, 2016). "Interference with FOXO1 expression was able to reverse the endothelial dysfunction of PMVECs caused by Hcy, suggesting that Hcy might exert its damaging effect on the vascular endothelium by upregulating FOXO1." (PMID 37491880, 2023). "FoxO1 may contribute to the genetic predisposition to develop endothelial dysfunction and cardiovascular disease." (PMID 35607519, 2022). "In brief, our current study provided the first evidence that mitochondria-targeted TPP-HT effectively prevented lipotoxicity-induced endothelial dysfunction by activating FoxO1 and Nrf2 nuclear translocation." (PMID 36671037, 2023). "In brief, our findings suggest that mitochondria-targeted TPP-HT prevents lipotoxicity induced endothelial dysfunction by enhancing mitochondrial function and redox balance by promoting FoxO1 and Nrf2 nuclear translocation." (PMID 36671037, 2023). "Dysregulated FOXO1 expression and activity appear to promote endothelial dysfunction, myocardial oxidative stress, cardiomyocyte cell death and inflammation observed in DCM." (PMID 26956801, 2016). "This study identifies the PI3K/Akt/FOXO1 signalling axis as a key regulator of PlGF expression and unifying pathway by which PlGF may contribute to common disorders characterised by endothelial dysfunction, providing a target for therapy." (PMID 34381074, 2021). "One of Sirt1 targets genes is the transcription factor forkhead box protein O1 (FoxO1), which, in the cardiovascular system, participates in myocardial metabolic stress adaptation, oxidative stress, endothelial dysfunction, and other processes related to inflammation and apoptosis." (PMID 34803741, 2021). "Thus, the exact mechanisms of the SIRT1/FOXO1 pathway and its regulatory roles in endothelial dysfunction and angiogenesis should be analyzed under specific circumstances." (PMID 31068817, 2019). "Metabolic alterations, oxidative stress, endothelial dysfunction, inflammation and apoptosis have been shown to be implicated in the development and progression of DCM, and also in the desirable processes for the regulation of FOXO1 gene." (PMID 26956801, 2016). "The responses in the heart such as metabolic adaptation, oxidative stress, endothelial dysfunction, inflammation, and apoptosis in which FOXO1 could participate that may lead to DCM are illustrated below." (PMID 26956801, 2016). "Besides eNOS regulation, gain of function of FOXO1 in vascular endothelial cells further increased iNOS mRNA with resultant endothelial dysfunction." (PMID 26956801, 2016). "FOXO1 inhibits the transcription of endothelial nitric oxide synthase and upregulates the expression of inducible nitric oxide synthase to cope with oxidative stress which leads to the production of peroxynitrite and endothelial dysfunction, and thereby promotes AS formation." (PMID 31719822, 2019). "Punicalagin, which is extracted from Punica granatum L., can promote mitochondrial biogenesis through the forkhead box O1 (FOXO1) pathway and improve hyperlipidemia-induced endothelial dysfunction." (PMID 40093324, 2025).
endothelial dysfunction (continued). "In this review, we focus on the FOXO1 pathway and its role in various processes that have been related to DCM, such as metabolism, oxidative stress, endothelial dysfunction, inflammation and apoptosis." (PMID 26956801, 2016). "Because FOXO1 contributes to endothelial dysfunction and has been shown to directly bind to the ICAM-1 promoter and activate ICAM-1 transcription, it is plausible to speculate that SIRT6 might modulate oxLDL-induced ICAM-1 expression by targeting FOXO1." (PMID 35246513, 2022).
liver cancer (18 papers, 2016 to 2025). An epithelial or non-epithelial malignant neoplasm that arises from the liver. "In summary, CK inhibited liver cancer cells proliferation by regulating p-FOXO1 level and induced ferroptosis." (PMID 38664638, 2024). "The research indicated that CK activated the FOXO signaling pathway by inhibiting the p-FOXO1 to induce the occurrence of ferroptosis in liver cancer cells and then exerted the anticancer effect." (PMID 38664638, 2024). "In order to ascertain the interaction between miRNA and target mRNA, Cyld/Foxo1 protein expression after the transfection of HepG2 liver cancer cells with an miR-182-5p mimic or antagomir was tested." (PMID 37298191, 2023). "Taken together, our data suggested that TKI-induced upregulation of TRIM15 is mediated by the AKT/FOXO1 axis in liver cancer cells." (PMID 36670097, 2023). "Then, we also demonstrated that treatment with FOXO1 inhibitors downregulated TRIM15 expression in liver cancer cells." (PMID 36670097, 2023). "For example, miR-590-5p exacerbates liver cancer expansion and chemoresistance by directly acting on FOXO1." (PMID 34867446, 2021). "Moreover, we demonstrated that FOXO1 silencing attenuated the increase in TRIM15 expression induced by regorafenib or sorafenib treatment in liver cancer cells." (PMID 36670097, 2023). "To further explore the effect of CK inducing ferroptosis in liver cancer cells through FOXO pathway, we used AS1842856, a specific inhibitor of FOXO1 protein." (PMID 38664638, 2024). "Also, miR-590-5p could boost the malignant behaviors of liver cancer by interacting with FOXO1." (PMID 36304989, 2022). "In liver cancer, SYVN1 promotes the proliferation, metastasis, and immune evasion of liver cancer cells through the ubiquitination and degradation of substrate proteins such as PTEN and FoxO1." (PMID 40877231, 2025). "Serum concentrations of miR-27a are significantly enriched in obese liver cancer patients relative to concentrations in both non-obese liver cancer patients and normal people, where ectopically expressed miR-27a reduces the function of FoxO1 proteins in HepG2 cells." (PMID 33804729, 2021).
viral infection (18 papers, 2015 to 2025). "In a chronic model of viral infection, deletion of FOXO1 leads to a decrease in memory T cells and loss of viral control over time, making FOXO1 a prime candidate to improve the stemness of a CAR-T product." (PMID 37880715, 2023). "Studies indicate that FoxO transcription factors such as FoxO1 and FoxO3 regulate immune responses to viral infections." (PMID 38674337, 2024). "Facing viral infection, autophagy is activated with the aid of phosphorylated FoxO1 and Atg7, which promotes the development and function of NKT cells against viral infection." (PMID 36230955, 2022). "This study suggests FoxO1 as a novel target for therapeutic intervention of viral diseases or IRF3-driven pathology." (PMID 33805458, 2021). "The activity of the transcription factor FOXO1 has been shown to increase upon mTOR inhibition during chronic viral infections and increased expression of co-inhibitory receptors such as PD-1." (PMID 29228684, 2017). "We also demonstrate that FoxO1-mediated autophagy is essential for effector functions of NK cells against viral infection." (PMID 27010363, 2016). "Thus, we believe that IBDV infection activates PD-1-induced autophagy via the PI3K/AKT/FoxO1 signaling pathway to support viral infection." (PMID 40692791, 2025). "While virus infection was required for FoxO1-mediated negative regulation of IRF3, the mRNA level of FoxO1 remained unchanged post-infection, suggesting posttranslational control of FoxO1 activity." (PMID 33805458, 2021). "During an acute virus infection, TFR-derived IL-10 is important for regulating Foxo1 activity and the capacity of GC B cells to down-regulate CXCR4 and cycle between the DZ and LZ of the GC." (PMID 33529242, 2021). "Our data also indicated for the first time in the context of viral infection that Tfh cells express KLF2 and Foxo1, which are inhibitory transcriptional factors responsible for arresting CXCR5 and Bcl-6 expression." (PMID 26640894, 2015). "Notably, AKT1, FOXO1, and MMP9 were enriched in the RIG-I-like receptor and Toll-like receptor pathways, which are crucial for innate immune responses against viral infections." (PMID 40574839, 2025). "To test this hypothesis, we analyzed the expression of FoxO1 and FoxO3 in response to the immunostimulants poly (I:C) and IFN-β, which mimic viral infection and elicit an antiviral response, respectively." (PMID 36016282, 2022).
Autoimmunity (17 papers, 2010 to 2024). The occurrence of an immune reaction against the organism's own cells or tissues. "Mice with a conditional knock out of FoxO1 in Treg demonstrated severe autoimmunity with a loss of Treg function, demonstrating the importance of FoxO1 in the induction and maintenance of Treg." (PMID 36710922, 2023). "This miRNA cluster is connected to the pathogenicity of Th17 due to pathogenic cytokine production, including IL-17A and IL-17F, and mediates autoimmunity by repression of FOXO1 and induction of IL-1R1 expression." (PMID 37834058, 2023). "T cell-specific deletion of Foxo1 led to autoimmunity because of decreasing FOXP3+ Treg cells while increasing T follicular helper in vivo." (PMID 37120440, 2023). "In fact, it activates Forkhead box protein O1 (FOXO1), a regulator of the expression of Foxp3 (a key transcription factor in Tregs), whose loss favors the development of autoimmunity." (PMID 31060286, 2019). "Loss of FOXO1 and FOXO3 in T cells results in uncontrolled T cell activation and autoimmunity, which is at least in part linked to defects in the generation of regulatory T cells." (PMID 23378844, 2013). "The expression of a constitutively active form of Akt enhances the differentiation of all Th subsets including Th17 cells, and T-cell-specific deletion of Foxo1 and Foxo3a results in the autoimmunity with an increased Th17 differentiation in vivo." (PMID 23383714, 2013). "The autoimmunity in STK4 deficiency may also be due to the defective regulation of development and function of regulatory T cells through modulation of FOXO1/FOXO3." (PMID 39339890, 2024). "Foxo1 and Foxo3a directly bind to Foxp3 promoter and increase the expression of Foxp3, and the deletion of Foxo results in the collapse of T-cell homeostasis and in the severe autoimmunity." (PMID 23383714, 2013). "Therefore, we speculate that the development of BBR in improving POF may be involved in regulating cell apoptosis and autoimmunity by regulating the PTEN/AKT1/FoxO1 pathway and Bim and Fas/FasL targets." (PMID 35420511, 2022). "FOXO1 represses TBX21-mediated effector functions to promote memory CD8+ T cell formation and Treg function; thus, a loss of FOXO1 may drive continued T cell effector function in the skin during melanocyte autoimmunity." (PMID 33384688, 2020). "Therefore, the upregulation of miR-96-182-83 in lupus lymphocytes may cause the decrease of Foxo1/3a and/or MITF, which in turn leads to the hyperactivation of B and T lymphocytes, immune tolerance breakdown and development of autoimmunity." (PMID 21170274, 2010). "Additionally, FOXO1 silencing promoted monocyte expansion, which was concomitant with exacerbation of SLE-like autoimmunity." (PMID 36105797, 2022). "Unlike the seemingly opposing effects on T cell survival, FOXO1 and FOXO3 co-operatively protect against autoimmunity." (PMID 23378844, 2013).
type 1 diabetes (16 papers, 2009 to 2025). "The loss of FOXO1 in osteoprogenitor cells can also reduce the loss of cancellous bone mass in type 1 diabetes (T1DM) mice." (PMID 35701780, 2022). "In a type 1 diabetes model, impaired insulin signaling promoted cardiac oxidative stress by activating FOXO1 and the expression of PPARα in cardiomyocytes." (PMID 40313619, 2025). "FoxO1 regulates glucose and fatty acid metabolism in cardiac mitochondrial dysfunction in type 1 diabetes." (PMID 38791311, 2024). "The transcriptional activity of FoxO1 decreased in the kidney from type 1 diabetic rodents induced by streptozotocin (STZ) and the podocytes cultured under high-glucose (HG) condition." (PMID 33859563, 2021). "Collectively, we demonstrated that FoxO1 as a novel trigger for the progression of type 1 diabetes‐induced vascular remodelling via its initiation of NLPR3 inflammasome‐dependent inflammation." (PMID 33108705, 2020). "To further investigate the role of FoxO1 in the pathological process of type 1 diabetes‐induced vascular remodelling, we examined the expression of α‐smooth muscle actin (α‐SMA), a contractile state SMCs‐specific protein marker in carotid arteries." (PMID 33108705, 2020). "The 3‐phosphoinositide‐dependent protein kinase 1 (PDK1)/FoxO1 pathway is important in regulating glucose and energy homeostasis, but little is known about its role in type 1 diabetes‐induced vascular remodelling." (PMID 33108705, 2020). "In summary, in this study, we examined the expression levels of APN and FoxO1 to explore the potential role of these two proteins in the pathology of type 1 diabetes-induced NAFLD." (PMID 30186875, 2018). "Administration of pharmacological FoxO1 inhibitor ameliorated type 1 diabetes‐induced vascular remodelling through decreasing the expression of pro‐inflammatory factors, NLRP3 inflammasome activation, adhesion factors, MMPs and apoptosis, reversing the SMCs phenotypic switching." (PMID 33108705, 2020). "We hypothesized that cardiac FOXO1 over‐activation was attributable to the imbalanced myocardial oxidative metabolism and mitochondrial and cardiac dysfunction in type 1 diabetes." (PMID 32450616, 2020). "Biotin administration was reported to suppress Foxo1 expression in the liver of type I diabetes rats, while no change was observed in Foxo1 expression in the liver and adipose tissue of biotin-supplemented mice." (PMID 39125325, 2024).
synovial sarcoma (15 papers, 2017 to 2026). "Activation of FOXO1 transcriptional activity in synovial sarcoma promotes apoptosis and autophagy, suggesting a potential role for FOXO1 in mediating the therapeutic response to quisinostat." (PMID 41319167, 2025).
esophageal squamous cell carcinoma (14 papers, 2018 to 2025). Esophageal squamous cell carcinoma (ESCC) is a type of esophageal carcinoma (EC) that can affect any part of the esophagus, but is usually located in the upper or middle third. "Paradoxically, FOXO1 was upregulated in esophageal squamous cell carcinoma (ESCC) tissue compared to normal tissue and was associated with reduced survival." (PMID 37174744, 2023). "The expression and activation of FOXO1 in esophageal squamous cell carcinoma induce TGFβ1 expression and make these cancer cells significantly resistant to chemotherapeutic agents." (PMID 38125769, 2023). "In this study, we characterized the prognostic value of FOXO1 and the interaction between tumor-derived FOXO1 and M2 macrophages in esophageal squamous cell carcinoma (ESCC)." (PMID 33052231, 2020). "For example, it was reported that FOXO1 could facilitate esophageal squamous cell carcinoma (ESCC) tumor progression by promoting M2 macrophage infiltration." (PMID 36475339, 2023). "For example, FOXO1 activates DNM3OS in esophageal squamous cell carcinoma." (PMID 34834139, 2021). "In addition, activation of FOXO1 in esophageal squamous cell carcinoma upregulates cancer-associated fibroblasts and promotes the secretion of TGF-β1, thereby inducing cisplatin and paclitaxel resistance in esophageal squamous cell carcinoma cells." (PMID 34123834, 2021).
ischemia (14 papers, 2014 to 2025). A hypoperfusion of the BLOOD through an organ or tissue caused by a PATHOLOGIC CONSTRICTION or obstruction of its BLOOD VESSELS, or an absence of BLOOD CIRCULATION. "Although we assume that the gene modification of Prkci or Foxo1 is the primal cause for the morphologic changes in the vasculature, we cannot exclude a possibility that ischemia induced by the inner shunts discussed in S3 Text causes hyper-branching at the angiogenic front." (PMID 34133418, 2021). "Exosomes derived from bone marrow mesenchymal stem cells target FOXO1 via miR-183 to reduce apoptosis and oxidative stress in ischemia/reperfused cardiomyocytes, thereby improving cardiac function and preventing myocardial ischemia/reperfusion (MI/R) injury." (PMID 41154662, 2025). "We here demonstrate that C/EBP-β is activated through phosphorylation in the leucine zipper domain by Mst1 through a FoxO1-dependent mechanism, thereby protecting the heart against ischemia." (PMID 39060225, 2024). "For these functions of FoxO1, different measures and treatments were applied to FoxO1 after ischemia." (PMID 35371601, 2022). "In the current study, involvement of p47phox-dependent production of ROS in the nuclear translocation of FOXO1 was analyzed in H9c2 cells following 4 h of metabolic inhibition (MI), which mimics the effects of ischemia." (PMID 29956081, 2018). "We here show that the acetylation level of FoxO1, an important target of Sirt1 in mediating cardioprotection, was increased during ischemia and was partially restored by NMN administration." (PMID 24905194, 2014). "METTL14 promotes endothelial inflammation and atherosclerotic plaque formation by mediating m6A modification of forkhead box O1 (FOXO1), and ischemia-induced ALKBH5 facilitates endothelial angiogenesis by mediating demethylation of sphingosine kinase 1 (SPHK1)." (PMID 36830642, 2023). "Combined deletion of FoxO1 and FoxO3 specifically in cardiomyocytes results in increased cardiac injury following acute ischemia and reperfusion in vivo, suggesting that FoxO1 and FoxO3 protect the heart from oxidative stress (Sengupta, Molkentin, Paik, DePinho, & Yutzey, 2011)." (PMID 31264342, 2019). "Post translational modifications of FOXO1 following ischemia that result in nuclear translocation and activation following ischemia have been well described in the mouse and rat cardiomyocytes and in H9c2 cells, but also in the mouse liver and in gerbil and mouse neurons." (PMID 29956081, 2018). "However, FOXO1 appears to respond to multiple cell stress and survival signals and, depending on the presence and magnitude of these signals, p47phox-induced ROS production and FOXO1 may be critically involved in cell fate decisions following ischemia." (PMID 29956081, 2018). "Myocardial ischemia significantly increased acetylation of FoxO1, a major target of Sirt1, whereas NMN significantly attenuated ischemia-induced increases in FoxO1 acetylation." (PMID 24905194, 2014).